HIF1A (hypoxia inducible factor 1 subunit alpha)
Diseases named in the same sentence as HIF1A in open-access papers (continued):
Sharing a sentence is not in itself a finding about the gene and the disease.
colitis (continued). "In left colitis of the lesions (E2 location), HIF-1α correlated strongly and significantly with TWI score (r =0.710, p = 0.007) and with ESR (r =0.620, p = 0.0024)." (PMID 38137357, 2023). "In both human IBD and experimental colitis, hypoxia-induced HIF1A is critical for many mucosal barrier-protective genes and angiogenesis." (PMID 37047397, 2023). "In the TNBS colitis model, Tnfa, Il1b1, and Hif1a, the latter predominantly in the preventive trials, built interesting correlation networks, thereby highlighting the fact that they are the cytokines that drive the inflammatory process in female animals." (PMID 37047397, 2023). "Mice with knockout of myeloid HIF-1α (Lyz2-Cre/HIF-1α+f/+f), on the other hand, exhibited moderate colitis and had less invaded immune cells." (PMID 36768744, 2023). "HIF-1α-overexpressing MSCs showed a superior immune regulation effect on colitis mice, but there is still insufficient research comparing this effect with that of primary MSCs." (PMID 36979804, 2023). "In IBD, HIF-1α is recognized as a protective factor since it helps preserve the functions of the intestinal barrier during colitis through the expression of barrier-protective genes, such as ITF and CD73." (PMID 36634466, 2023). "Clinical symptoms of murine TNBS-colitis are exasperated when HIF-1α is decreased and, conversely, overexpression of HIF-1α can be protective." (PMID 37375100, 2023). "Moreover, DSS-treated mice administered concurrently with l-clodronate show milder clinical symptoms of colitis, intestinal transit times similar to control animals, and decreased expression of factors implicated in neural inflammation and death, including Bax, Hdac4, IL-18, Casp8 and Hif1a." (PMID 38105266, 2023). "Pharmacological activation of the HIF1α pathway promotes mucosal regeneration and intestinal barrier function in several mouse models of colitis, as recently reviewed by Colgan & Taylor." (PMID 38163085, 2023). "The NF‐κB signaling pathway is an important downstream pathway of HIF‐1α,20, 21 and the HIF‐1α/NF‐κB signaling axis is involved in the regulation of multiple pathological processes such as colitis and spinal cord injury." (PMID 37475697, 2023). "What’s more, accumulating evidences have elicited the stimulative role of HIF1A in experimental colitis." (PMID 35764613, 2022). "Current IBD therapies such as corticosteroids, and 5-aminosalicylate, modulate colitis by blocking mammalian target of the rapamycin complex 1 (mTORC1), which results in decreasing HIF-1α expression and thereby glycolysis." (PMID 36405760, 2022). "The expression of tight junction proteins (occludin, ZO-1), HIF-1α as well as VDR was up-regulated in colitis mice with hypoxia stimulation." (PMID 35711312, 2022). "Tiliroside attenuates disease activity in mice with colitis, where it promotes HIF-1α enzyme degradation." (PMID 36761171, 2022). "Previous research has proven that stabilization of HIF-1α exerts an anti-inflammatory effect by inhibiting the expression of pro-inflammatory cytokines in murine colitis." (PMID 35620283, 2022). "HIF1A has been reported to accelerate inflammatory responses and 1,25(OH)2D3 signaling has recently been proposed by others to inhibit colitis by inhibiting HIF1A activation in colonic epithelial cells." (PMID 35779631, 2022). "Studies have confirmed that intestinal epithelial HIF-1α is an important protective factor against colitis and can effectively alleviate inflammatory colonic injury." (PMID 35399629, 2022). "And other studies have revealed that disruption of epithelial HIF-1α resulted in decrease of TJPs and increased epithelial permeability in colitis and eosinophilic esophagitis." (PMID 35492370, 2022). "Shah found that in colitis activation of HIF-1α leads to a protective response, while chronic activation of HIF-2α increases proinflammatory response, intestinal injury and cancer." (PMID 35576220, 2022).
colitis (continued). "Some studies reported that the expression of IL-10 in the colon was reduced in mice with DSS-induced colitis, and Wogonin enhanced IL-10 production by inducing transcript factor HIF-1α expression via the AKT/GSK3β signal pathway." (PMID 36176442, 2022). "The HIF-1α/glycolytic pathway disrupts balance of M1/M2 macrophages and the secretion function of neutrophils to affect the pathological state of colitis." (PMID 36761171, 2022). "The current study aims to investigate the mechanism of MTA1/HIF1A/AQP4 axis in experimental colitis in mice." (PMID 35764613, 2022). "This has led to the approach of pharmacologically stabilizing intestinal HIF-1α to protect against colitis and this has progressed to clinical trials." (PMID 35769556, 2022). "Our study showed that MLT mediated butyrate-improved SD-induced colitis through the MCT1/HDAC3/P-GSK-3β/HIF-1α/NF-KB loop." (PMID 34769321, 2021). "HIF1α enhances the epithelial barrier function and a conditional HIF1α knockout exacerbates colitis in mouse models, indicating a protective role of HIF1 in the guts." (PMID 33919829, 2021). "As has been reported, Jian-Pi Qing-Chang treatment attenuated the intestinal epithelial permeability and inflammation by inhibiting NF-κB/HIF-1α pathways in colitis mice." (PMID 33542787, 2021). "The differential roles of HIF-1α vs HIF-2α in the intestinal epithelial cells have been well-studied in experimental colitis models." (PMID 33519819, 2020). "In this study, we observed that miR-155 inhibition by antagomir treatment ameliorated DSS-induced colitis in mice and improved the expression of HIF-1α." (PMID 32713852, 2020). "We found that HIF-1α was increased in HIF-2α-KO Treg cells re-isolated from RAG-1-KO mice with colitis." (PMID 33024109, 2020). "Additional Hif1a deletion restored the capacity of Cd4CreHif2af/f tTreg cells to suppress effector T cell-induced colitis in RAG-1-KO mice, as shown by retention of body weight and repression of colitis score." (PMID 33024109, 2020). "In conclusion, miR-155 treatment decreased the expression of HIF-1α in DSS-induced colitis mouse colonic tissues while miR-155 antagomir or FG-4497 treatments rescued this reduction, eliciting intestinal barrier protective function." (PMID 32713852, 2020). "FG-4497-induced HIF-1α provides an overall beneficial influence on trinitrobenzenesulfonic acid (TNBS)-induced colitis, mainly because of its barrier protective functions." (PMID 32713852, 2020). "Several groups have already published diverging roles of HIF-1α in different cell types in DSS colitis." (PMID 33202783, 2020). "Along those lines, expression of HIF1α in intestinal dendritic cells, which are crucial for the maintenance of mucosal immune homeostasis, suppresses colitis-induced inflammation." (PMID 33257753, 2020). "MiR-155 is increased in colitis and downregulates expression of hypoxia-inducible factor 1α (HIF-1α)." (PMID 32713852, 2020). "In our group, a HIF-1α knockout in myeloid cells led to reduced clinical signs of a dextran sodium sulfate (DSS)-induced murine colitis with an increased presence of regulatory T-cells (Tregs)." (PMID 33202783, 2020). "Consistent with the role of ROS in inflammatory hypoxia, most CGD patients manifest inflammatory bowel disease–like symptoms, and pharmacological stabilization of HIF-1α within the mucosa protected CGD mice from severe colitis." (PMID 31719116, 2019). "We have performed immuno-histochemistry and ELISA assays on colon tissue samples to quantify the activity of HIF-1a and nuclear p65 during active inflammation in experimental colitis." (PMID 30430451, 2019). "Accordingly, inflammation and granuloma formation were impaired and survival increased in CGD mice with colitis or aspergillosis upon Tβ4 treatment or HIF-1α stabilization." (PMID 31719116, 2019). "The aims of this study are to enhance bioavailability and investigate their impact on nuclear p65 and HIF-1α for the first time in experimental colitis." (PMID 30430451, 2019).
colitis (continued). "HIF-1α is important for mucosal repair, and its signaling cascade has been shown to be protective against colitis." (PMID 31976310, 2019). "In lung aspergillosis, and likely in DSS-induced colitis, the effects of Tβ4 were dependent on HIF-1α that mediated not only the induction of autophagy but also the up-regulation of hypoxia-responsive genes." (PMID 31719116, 2019). "Further study with IELs subpopulations in Hif1-αΔIEC mice by using flow cytometry also confirmed the importance of Hif1-α in the development of DSS-induced colitis." (PMID 31040849, 2019). "Previous research has documented also that neutrophils play a very important role in resolution of intestinal inflammation, but the outcome of neutrophil-cell-specific deletion of HIF-1α in vivo during colitis is for the moment poorly understood." (PMID 29762526, 2018). "Previous studies have also emphasized a protective role for HIF-1α in a dextran sodium sulfate (DSS)-induced model of murine colitis, which is a mouse model of Inflammatory bowel disease (IBD)." (PMID 29762526, 2018). "In TNBS-induced murine colitis, another prolyl hydroxylase inhibitor stabilized HIF-1α levels and afforded protection in a similar manner." (PMID 29304733, 2018). "Comparable results have been shown in experimental colitis with deletion of HIF-1α in dendritic cells and T-cells." (PMID 29261815, 2017). "This is in contrast to the inflammation-dampening role of HIF-1α in dendritic cells in the same colitis model." (PMID 29261815, 2017). "Hypoxia and HIF-1α activation are protective in mouse models of colitis, and the latter regulates autophagy." (PMID 28740109, 2017). "Using mice with a conditional knockout of HIF-1α in myeloid cells in a DSS-induced model of colitis we report a disease promoting role of myeloid HIF-1 during intestinal inflammation." (PMID 29261815, 2017). "Using similar mouse models, moderate or high overexpression of HIF-1α leads to a decrease in intestinal damage in a colitis model, as expected." (PMID 26812949, 2016). "In our study we found a strong correlation between HIF-1α and IL-6 mRNA levels suggesting involvement of HIF-1α in transcriptional regulation of IL-6 gene during colonic inflammation and HBO2." (PMID 27656047, 2016). "Results demonstrate that HBO2 has an anti-inflammatory effect in DSS-induced colitis in mice, and this effect is at least partly dependent on expression of HIF-1α and antioxidative genes." (PMID 27656047, 2016). "HIF-1α activation in colitis leads to a protective response, whereas chronic activation of HIF-2α increases the pro-inflammatory response, intestinal injury, and cancer." (PMID 26812949, 2016). "Treatment with a HIF-1α agonist boosts the innate immune response of the intestinal epithelium in a murine colitis model." (PMID 27002817, 2016). "Strong correlation of HIF-1α mRNA level to GPx1, SOD1, and IL-6 mRNA expression suggests involvement of HIF-1α in transcriptional regulation of these genes during colonic inflammation and HBO2." (PMID 27656047, 2016). "PHDs inhibitors, which activate HIF-1α and HIF-2α, are protective in acute colitis models through a HIF-1α-dependent mechanism." (PMID 26812949, 2016). "Herein, it was provided evidence that HBO therapy is essential to control the level of HIF-1α and therefore improve colitis by TNBS-induced." (PMID 25926972, 2015). "Our findings share similarities with recent studies in colitis and corneal infection models, where HIF-1α ultimately acted to suppress inflammation in the affected tissues." (PMID 25927232, 2015). "HIF1α that is expressed by T cells is also protective in the dextran sodium sulfate (DSS) model of colitis." (PMID 26183215, 2015). "Conversely, knockout of HIF-1α can ameliorate the pathological manifestations of colitis." (PMID 41378888, 2026). "We observed that targeting the PHD/HIF-1α axis with RXD decreased body weight loss and the colitis disease activity index (DAI) in WT mice but not in Hif1a cKO mice." (PMID 39543372, 2025).
colitis (continued). "In addition, activation of HIF-1α in myeloid cells exacerbates the manifestation of colitis, whereas specific knockdown of the gene in myeloid cells significantly ameliorates colitis." (PMID 40243444, 2025). "Additionally, GTA treatment increased acetyl-CoA levels and downstream histone H3K27 acetylation at the Sα region in B cells from Hif1a cKO mice during DSS-induced colitis." (PMID 39543372, 2025). "We propose the hypothesis that vitamin D may ameliorate the DSS-induced colitis by suppressing the HIF-1α/GATA1/STING signaling pathway." (PMID 40563965, 2025). "Notably, treatment with GTA alleviated the symptoms of colitis in both Hif1a cKO mice and control mice after DSS exposure, as indicated by improvements in body weight, colon length and histology." (PMID 39543372, 2025). "In addition, IgA+ cell numbers and secreted IgA levels were lower in Hif1a cKO mice than in littermate control mice during DSS-induced colitis." (PMID 39543372, 2025). "In contrast, other studies argued that activation of HIF-1α in immune cells may lead to colitis in mice." (PMID 40691131, 2025). "The increase in the relative abundance of Mucispirillum in the DSS group may have resulted in the inhibition of HIF1α expression and reduced the number of goblet cells, thus contributing to the development of colitis." (PMID 40806121, 2025). "HIF-1α belongs to the hypoxia-inducible factor family and has been shown to be a key regulator of barrier integrity during colonic mucosal injury, and deficiency of HIF-1α in IECs would exacerbate DSS-induced colitis." (PMID 40691131, 2025). "Huangqin decoction ameliorates DSS-induced colitis by inhibiting the Ras-PI3K-Akt-HIF-1α pathway." (PMID 38902425, 2024). "However, in IBD and murine colitis, hypoxia-driven HIF-1α in macrophages activates Wnt/mTOR pathways, disrupting autophagy in IEC." (PMID 38605960, 2024). "However, focused research on HIF-1α in SCFAs-modulated colitis macrophages remains scarce, representing a promising research avenue, especially given its importance in conditions like pneumonia." (PMID 38605960, 2024). "Moreover, HIF-1α activation has been demonstrated to reduce intestinal inflammation and protect against colitis in mouse models." (PMID 39719983, 2024). "Both p70S6K1 and HIF1α are crucial molecular regulators of inflammation and colitis severity." (PMID 39457040, 2024). "In the preventive trial with DSS-colitis, dexamethasone-induced an increase in Hif1a and Il6, and a decrease in Tjp1 expression compared to controls, while Tgfb1 and Vegfa expression was increased in the MTADV group, as well as Nos2 and Tjp1 in comparison to dexamethasone." (PMID 37047397, 2023). "Dark tea has also been shown to alleviate colitis induced by dextran sodium sulfate and reduce the expression level of inflammatory factors, mainly by regulating the NF-κB and HIF-1α signaling pathways, regulating gut bacteria, and enhancing the synthesis of short-chain fatty acids such as butyrate." (PMID 37764687, 2023). "HIF-1α linked well with the degree of UC lesions in our study, with a strong and significant correlation seen between it and the TWI score in both pancolitis and left colitis forms." (PMID 38137357, 2023). "Transplantation of HIF-1α-overexpressing MSCs in mice with experimental colitis resulted in good immune balance and mucosal rehabilitation, thereby proving a potentially effective treatment for IBD or other inflammatory diseases that can be applied in the future." (PMID 36979804, 2023). "Myeloid knockout of HIF-1α ameliorated murine dextran sodium sulfate (DSS)-induced colitis while myeloid HIF-2α knockout aggravated colitis by increasing myeloperoxidase (MPO)+ and CD3+FoxP3+ T regulatory cell recruitment deep in the colon with no apparent differences in F4/80+ cell infiltration." (PMID 37124241, 2023).
colitis (continued). "HIF-1α has a critical role in maintaining barrier function and mice deficient in HIF-1α have increase intestinal permeability and barrier function in the context of DSS colitis." (PMID 36742292, 2023). "First, the role of Hif1α in regulatory T cells seems to be debatable in an animal model of colitis." (PMID 37809060, 2023). "Butyrate can alleviate DSS-induced colitis by regulating autophagy via HIF-1α." (PMID 37868958, 2023). "In epithelium-specific mice with HIF-1α deficiency, the therapy did not prevent colitis, indicating that epithelial HIF-1α is a tissue target for AKB-4924-mediated protection." (PMID 36768744, 2023). "Thus, we aim to examine the efficacy of hypoxia-inducible factor (HIF)–1α-overexpressing MSC (HIF-MSC) transplantation in experimental colitis and investigate the immunity regulation mechanisms of HIF-MSC through macrophages." (PMID 36979804, 2023). "This may require further studies, such as RNA sequencing, to explore the specific mechanisms of HIF1α-overexpressing optimized MSCs in other aspects of therapy for colitis." (PMID 36979804, 2023). "Moreover, conditional knockout of HIF1α exacerbated inflammation in TNBS-induced colitis in mice, while increased HIF1α activation via knock-out of the von Hippel–Lindau (VHL) gene was protective." (PMID 38163085, 2023). "The anti-colitis role of tiliroside might be achieved by regulating HIF-1α modulated glycolysis and thus inducing macrophage reprogramming in the colon." (PMID 37876728, 2023). "Some studies have shown that modulating the activity of HIF-1α using traditional medicine could ameliorate colitis." (PMID 37876728, 2023). "Moreover, gut barrier disintegration, bacterial dissemination from the gut into lymphoid organs (mesenteric lymph nodes, spleen), and systemic Tnf levels in DSS-induced colitis was reduced by treatment with the HIF-1α inhibitor CG-598." (PMID 36232412, 2022). "The FOXP3 gene promoter in HIF1-α-/- Tregs fails to protect the animal from colitis caused by effector T cells, further demonstrating the role of HIF1-α in the suppressive functions of Tregs." (PMID 35585983, 2022). "A recent study showed that HIF-2α was a potential inhibitor of HIF-1α activity, and knockout of HIF-2α in Treg cells relieved its suppression of HIF-1α and thereby impaired the Treg capacity to inhibit effector T-cell-induced colitis and airway allergic inflammation." (PMID 35948909, 2022). "Indeed, CSE/H2S system activity to stabilize nuclear translocation of HIf1α was shown to promote the resolution of inflammation and injury during colitis, and H2S donor molecules further enhance this protection." (PMID 36520801, 2022). "HIF-1α plays a protective role in DCs, T cells, and epithelial cells in murine colitis." (PMID 36761171, 2022). "Furthermore, analyses of GSE53835 indicated that HIF1A was overexpressed, while co-expression analysis by MEM exhibited that MTA1 and HIF1A were both markedly co-expressed and shared a positive correlation in experimental colitis." (PMID 35764613, 2022). "It was found that MTA1 and HIF1A were both highly-expressed in experimental colitis samples." (PMID 35764613, 2022). "Previous studies have showed that wogonin can be used to treat colitis by inducing the expression of transcription factor HIF-1α through the protein kinase B/glycogen synthase kinase β (AKT/GSK3β) signaling pathway to increase interleukin 10 (IL-10) production." (PMID 35399629, 2022). "Further, activation of HIF-1α attenuated C. difficile-induced colitis in mice." (PMID 33542787, 2021). "Considering that tiliroside dampens M1 macrophage polarization through accelerating the proteasomal degradation of HIF-1α in BMDMs, we then determined whether macrophages were responsible for the tiliroside-mediated alleviation of colitis." (PMID 33868286, 2021). "All of these activities of HIF-1α in colitis result in a protective response." (PMID 34502078, 2021).